WHRN (whirlin)
Description:
Involved in hearing and vision as member of the USH2 complex. Necessary for elongation and maintenance of inner and outer hair cell stereocilia in the organ of Corti in the inner ear. Involved in the maintenance of the hair bundle ankle region, which connects stereocilia in cochlear hair cells of the inner ear. In retina photoreceptors, required for the maintenance of periciliary membrane complex that seems to play a role in regulating intracellular protein transport.
Synonyms: DFNB31; CIP98; USH2D; PDZD7B; WI
Tractability: Antibody: its Gene Ontology location is reachable by antibodies, with medium confidence. PROTAC: ubiquitination databases record sites on it.
Gene: Protein-coding gene on chromosome 9 (114,402,078 to 114,505,525, reverse strand). Ensembl gene ENSG00000095397.
Subcellular location: Cytoplasm; Cell projection, stereocilium; Cell projection, growth cone; Photoreceptor inner segment; Synapse
Pathways (Reactome):
Sensory Perception: Sensory processing of sound by inner hair cells of the cochlea; Sensory processing of sound by outer hair cells of the cochlea
Gene Ontology:
Molecular function: identical protein binding; protein binding
Biological process: retina homeostasis; sensory perception of light stimulus; sensory perception of sound; auditory receptor cell stereocilium organization; detection of mechanical stimulus involved in sensory perception of sound; establishment of protein localization; inner ear receptor cell differentiation; inner ear receptor cell stereocilium organization; cerebellar Purkinje cell layer formation; paranodal junction maintenance
Cellular component: cytoplasm; cilium; neuronal cell body; periciliary membrane compartment; photoreceptor connecting cilium; photoreceptor inner segment; plasma membrane; stereocilia ankle link; stereocilia ankle link complex; stereocilium; stereocilium tip; synapse; USH2 complex; actin filament; ciliary basal body; growth cone; stereocilium bundle
Genetic constraint (gnomAD): Loss-of-function variants: 41 observed, 65.81 expected, observed/expected ratio (o/e) 0.62, 90% interval 0.48 to 0.81. The upper end of that interval is the gene's LOEUF score, 0.81, which puts it in group 3 of 6, group 1 being the genes least tolerant of losing a copy. Missense variants: 1,243 observed, 1,241.7 expected, observed/expected ratio (o/e) 1, 90% interval 0.95 to 1.05. Synonymous variants: 560 observed, 555.74 expected, observed/expected ratio (o/e) 1.01, 90% interval 0.94 to 1.08.
Gene-disease validity (ClinGen):
ClinGen rates the evidence that WHRN causes each of these diseases.
Usher syndrome type 2D (autosomal recessive): Definitive. Any Usher syndrome in which the cause of the disease is a mutation in the WHRN gene.
nonsyndromic genetic hearing loss (autosomal recessive): Moderate. A disease characterized by hearing loss that is not part of a larger syndrome.
Homologues: Orthologues: chimpanzee WHRN (99% identical), macaque WHRN (97% identical), pig WHRN (92% identical), rabbit WHRN (90% identical), guinea pig WHRN (90% identical), mouse Whrn (88% identical), rat Whrn (88% identical), dog WHRN (88% identical), zebrafish whrna (61% identical), tropical clawed frog whrn (58% identical), zebrafish whrnb (50% identical). Paralogues in human: PDZD7 (23% identical), USH1C (20% identical).
Diseases named in the same sentence as WHRN in open-access papers:
WHRN is named in the same sentence as 25 diseases in open-access papers, as found by Europe PMC text mining. Sharing a sentence is not in itself a finding about the gene and the disease. The quoted sentences say what the papers report.
Usher syndrome (29 papers, 2010 to 2025). A syndromic diseae characterized by the association of sensorineural deafness (usually congenital) with retinitis pigmentosa and progressive vision loss. "In mammals, Myosin 15A also traffics a known Usher syndrome protein, Whirlin (encoded by dyschronic in flies) to the tips of hair cell stereocilia as a cargo protein." (PMID 38412189, 2024). "The whirler mouse, a model of human Usher syndrome, which cannot produce functional whirlin proteins encoded by WHRN in the inner ear, manifested abnormally shortened stereocilia of both cochlear and vestibular HCs." (PMID 33983457, 2021). "Mutations in WHRN have previously been shown to cause autosomal recessive non syndromic deafness and Usher syndrome type 2D." (PMID 29270100, 2017). "The significant bulk of Whrn research has been performed in the ear and eye since human WHRN mutations contribute to a subset of Usher syndromes." (PMID 24011083, 2013). "At least nine genes have been identified as underlying Usher syndrome; yet most mouse mutants (except whirlin and usherin that cause type II Usher syndrome) bearing one of these mutations develop hearing deficits but not visual dysfunction." (PMID 23351659, 2012). "Of note, the only DFNB31 mutations reported in Usher syndrome are located within the coding region specific to the whirlin long isoform." (PMID 21738389, 2011). "Third, whirlin mutations that ablate the N-terminal PDZ domains lead to Usher syndrome, but non-syndromic hearing loss will result if they are spared." (PMID 20502675, 2010). "WHRN mutations occur in Usher syndrome, a neurosensory disorder affecting hearing and vision." (PMID 39747859, 2025). "Moreover, the C-terminus of RPGR interacts with whirlin, mutations of which result in Usher syndrome, and nucleophosmin, which functions in cell division." (PMID 34800980, 2021). "The HHD proteins whirlin and harmonin are implicated in Usher syndrome causing hearing-vision loss." (PMID 33361159, 2021). "These three scaffolding proteins are Whirlin (DFNB31), Harmonin (Ush1C) and the PDZ domain containing protein 7 (PDZD7), a deafness protein associated with the Usher syndrome." (PMID 33853521, 2021). "Usher syndrome is classified into three types, type I, II and III, and causal genes of type II include USH2A, ADGRV1, and WHRN (DFNB31)." (PMID 33105608, 2020). "The proteins encoded by these mutant genes, whirlin and myosin VIIA, are among several Usher syndrome proteins found to interact with usherin at the mouse periciliary membrane complex." (PMID 31998945, 2020). "The location of CLCC1 alongside GPSM2, which codes for the putative whirlin protein complex-interacting molecule, is interesting given the role of this complex in Usher syndrome." (PMID 30157172, 2018). "Whirlin (Whrn) is a PDZ domain-containing cytoskeletal scaffold whose absence in humans results in Usher Syndromes or variable deafness-blindness syndromes." (PMID 24011083, 2013). "However, myosin XV interacts with whirlin - a protein known to be involved in the Usher syndrome (USH2D)." (PMID 21479269, 2011). "The fly orthologue candidates of Usher syndrome genes MYO7A (crinkled in fly), WHRN (dyschonic in fly), USH1C (CG5921 in fly), and PCDH15 (Cad99C in fly) were localized or expressed in the actin-rich scolopale cells, consistent with our previous findings." (PMID 38412189, 2024).
deafness (24 papers, 2007 to 2025). An inherited or acquired condition characterized by the complete loss of the ability to hear from one or both ears. "Whirlin colocalizes and interacts with two other causal proteins for deafness, MYO15A (DFNB3) and EPS8 (DFNB102), forming a tripartite complex that controls actin polymerization and elongation of the actin core at the tips of the stereocilia." (PMID 35444606, 2022). "Comparative genomics identifies dysc as the closest Drosophila homolog of whirlin, a loci associated with nonsyndromic deafness and Type II Usher syndrome (USH2) in humans." (PMID 22532808, 2012). "CG34400 encodes for a protein homologues to human DFNB31 (Deafness, autosomal recessive 31) that causes congenital hearing impairment in DFNB31 deficient people and mouse whirlin, that causes deafness in the whirler mouse." (PMID 21943192, 2011). "Within the mapped region on chromosome 9, 102 genes were sorted using GeneDistiller, among which DFNB31, encoding whirlin, was the only gene already reported to be involved in rod-cone dystrophy associated with deafness as part of Usher syndrome type 2 (USH2D locus)." (PMID 21738389, 2011). "The whirler mouse mutant carries a spontaneous deletion within the C-terminus of whirlin, resulting in profound deafness, severe head-tossing, and vestibular defects." (PMID 38974964, 2024). "Mutations in the WHRN gene encoding whirlin, a PDZ domain molecule involved in stereocilia elongation, cause deafness, in particular in Usher syndrome type 2." (PMID 38203368, 2023). "Sequence analysis showed that two deafness-associated mutation sites in Whirlin (V460 and R490, NCBI Clinvar database, VCV000364688, and VCV000156029) are conserved between Whirlin and PDZD7, which are corresponding to V594 and R624 in PDZD7." (PMID 33937240, 2021). "The structural and biochemical characterization on the HHD domain can provide mechanistic explanations for human deafness mutations in both PDZD7 and Whirlin." (PMID 33937240, 2021). "Mutations in whirlin cause either Usher syndrome type II (USH2), a deafness-blindness disorder, or nonsyndromic deafness." (PMID 20502675, 2010). "It has been demonstrated that mutations in deafness, autosomal recessive 31 (DFNB31), the gene encoding whirlin, is responsible for nonsyndromic hearing loss (NSHL; DFNB31) and Usher syndrome type II (USH2D)." (PMID 20352026, 2010). "An absence of both whirlin isoforms causes abnormally short stereocilia and profound deafness and vestibular dysfunction." (PMID 35444606, 2022). "In addition, a nonsense mutation, p.R778X, and a single nucleotide deletion, c.2324delG, leading to a deletion of the C-terminus of the whirlin protein were found responsible for deafness DFNB31." (PMID 20502675, 2010). "For example, it could be hypothesised that transcripts of deafness-associated genes, MSRB3, ESPN, and WHRN, all in possession of extreme A + U/C + G compositions, are likely to be sensitive to any drug-mediated global dysregulation of expression, with ototoxicity a potential outcome." (PMID 40341320, 2025). "We found that A64D and R223H on WHRN, although not affecting binding to USH2A or ADGRV1, cause deafness by disturbing WHRN dimerization and disrupting phase separation of USH2 condensates." (PMID 36964137, 2023). "USH2A-CT(S) binds to WHRN NPDZ12 T110A with a weaker binding affinity (Kd = ~16 μM) than that of the WT (Kd = ~2.7 μM), which may contribute to deafness." (PMID 36964137, 2023). "To determine if the deafness causing mutation affects the ability to localize to the tips of filopodia, we over-expressed DsRed tagged CIB2WT and CIB2R186W constructs of human CIB2 along with non-tagged human Whirlin and GFP-Myosin 15a in COS-7 cells." (PMID 26426422, 2015).
hearing loss (9 papers, 2010 to 2026). "Variants in MYO7A, USH1C, CDH23, PCDH15, and WHRN are also responsible for non-syndromic hearing loss associated with loci DFNB2 and DFNA11, DFNB18, DFNB12, DFNB23, and DFNB31, respectively." (PMID 38525684, 2024). "Somewhat remarkable were the present findings of a deep HFE genealogy upstream a Swedish river valley segregating with Wilson ́s disease and LQTS was also segregating with hearing loss caused by mutations in WHRN and TMC1 respectively." (PMID 29270100, 2017). "USH2A, ADGRV1, and WHRN are the three known USH2 causative genes, which are also linked to isolated retinal degeneration and hearing loss." (PMID 41654259, 2026). "Among these elements, we identified six potential variants in cis-regulatory elements associated with hearing loss genes, CDH23, OTOF, MYO6, COL4A4 and WHRN." (PMID 40164689, 2025). "Mutations of MYO7A, CDH23, USH1C, PCDH15, USH1G, and WHRN can cause non-syndromic recessive hearing impairment, and MYO7A variants are also associated with a non-syndromic dominant form of hearing impairment." (PMID 35353227, 2022).
Usher syndrome type 2 (6 papers, 2011 to 2023). A syndrome characterized by congenital, bilateral sensorineural hearing loss that is mild to moderate in the low frequencies and severe to profound in the higher frequencies, no abnormalities in the vestibular system, and retinitis pigmentosa. "Mutations in DFNB31 coding WHRN protein can cause both ARNSHL and Usher syndrome Type 2 (MIM 607928)." (PMID 26561413, 2015). "Defects in the Whirlin gene, a PDZ (post-synaptic density, disc-large, Zo-1 protein domains) domain-containing scaffold protein, are responsible for both Usher syndrome type 2 and nonsyndromic hearing loss (DFNB31)." (PMID 21738395, 2011).
retinal degeneration (5 papers, 2010 to 2026). Degeneration of the retina. "Histological examination of the eyes from this cohort of animals found that the photoreceptor nuclear layer was significantly thinner and the outer segments shortened in the whirlin knockout mice, which are signs for retinal degeneration." (PMID 20502675, 2010). "Since usherin is required for maintaining the long term viability of photoreceptors, the absence of usherin from the PMC could be responsible, at least in part, for the late-onset retinal degeneration in whirlin knockout mice." (PMID 20502675, 2010). "Thus both functional and morphological assays indicate that the whirlin knockout mice develop late-onset retinal degeneration." (PMID 20502675, 2010). "The whirlin knockout mice characterized in this study have a late-onset retinal degeneration and a congenital, non-progressive hearing impairment." (PMID 20502675, 2010). "Retinal function tested by electroretinogram (ERG), a recording of the retinal electrical response to flashes of light, and histology examined by light microscopy did not reveal overt retinal degeneration in whirlin knockout mice up to 24 months of age (data not shown)." (PMID 20502675, 2010).
Usher syndrome type 1 (2 papers, 2023 to 2025). A syndrome characterized by congenital, bilateral, severe sensorineural hearing loss, abnormalities in the vestibular system, and adolescent-onset retinitis pigmentosa. "In addition to MYO7A (DFNA11, DFNB2, and Usher syndrome type I), OTOF (DFNB9), CDH23 (DFNB12 and Usher syndrome type I), and WHRN (DFNB31) are present within the hair cell or its stereocilia." (PMID 37289589, 2023).
hearing disorder (1 paper, 2016). A disorder characterized by the partial or complete loss of the ability to detect sounds due to damage to the ear structures or inability of the brain to properly interpret or process the auditory signals it receives from the anatomic structures of the ear. "WHRN (DFNB31) mutations cause diverse hearing disorders: profound deafness (DFNB31) or variable hearing loss in Usher syndrome type II." (PMID 27117407, 2016).
heart failure (1 paper, 2022). Inability of the heart to pump blood at an adequate rate to meet tissue metabolic requirements. "Carboxylesterase 1D (CES1D), whirlin (WHRN), and WNK lysine deficient protein kinase 2 (WNK2) were the three genes with random absolute values of LogFC and indicators of heart failure (natriuretic peptide B, NPPB) detected." (PMID 35886059, 2022). "The three genes with random absolute values of LogFC and indicators of heart failure (natriuretic peptide B, NPPB) were detected: carboxylesterase 1D (CES1D), whirlin (WHRN), and WNK lysine deficient protein kinase 2 (WNK2)." (PMID 35886059, 2022).
WHRN also shares sentences with these, for which no sentence is quoted: Deafness, autosomal recessive 31 (4 papers); Blindness (2); DOORS syndrome (1); glaucoma (1); Hearing impairment (1); hereditary hemochromatosis (1); long QT syndrome (1); nonsyndromic hearing loss (1); retinal ciliopathy (1); retinitis pigmentosa (1); Rod-cone dystrophy (1); sensorineural hearing loss (1); tumor (1); Usher syndrome type 2D (1); viral infection (1); Wilson ́s disease (1); Wolfram syndrome (1).